FBXO5 (F-box protein 5)
Diseases named in the same sentence as FBXO5 in open-access papers (continued):
Sharing a sentence is not in itself a finding about the gene and the disease.
uterine cancer (1 paper, 2021). Primary or metastatic malignant neoplasm involving the uterine corpus and/or the cervix. "Finally, FBXO5 is an F-box protein whose substrates remain largely unknown and has many “deleterious” and “possibly/probably damaging” alterations identified within colorectal and uterine cancers." (PMID 35008511, 2021).
cancer (31 papers, 2010 to 2025). A tumor composed of atypical neoplastic, often pleomorphic cells that invade other tissues. "FBXO5 gene expression is upregulated in many human cancers and is associated with chromosomal instability." (PMID 39411371, 2024). "Immune checkpoints, TMB, and MSI were also overtly associated with FBXO5 dysregulation among diverse kinds of cancers." (PMID 35720327, 2022). "This study constructed a detailed exploration of FBXO5 expression differences, underlying functions, and prognostic significance in 33 human cancers." (PMID 35720327, 2022). "Increased expression of FBXO5 has been shown to cause chromosomal instability and cancer initiation." (PMID 34203389, 2021). "Reviewing previous studies, we can find that FBXO5 not only plays an important role in the cell cycle but also plays a key role in cancer development, which clarifies the association between the cell cycle and cancer." (PMID 36004205, 2022). "The present research also discovered that FBXO5 expression was related to tumor prognosis, which suggested that the overexpression of FBXO5 was a hazard factor of cancers and could cause a poorer prognosis in terms of OS, DSS, PFI, and DFI." (PMID 35720327, 2022). "Depletion of FBXO5 enhances the sensitivity of human cancer cells to both chemotherapy and radiotherapy." (PMID 40534867, 2025). "Mechanistically, METTL16 enhances FBXO5 mRNA stability via m6A modification, leading to elevated FBXO5 expression, which promotes cancer cell proliferation, migration, invasion, and EMT." (PMID 41322419, 2025). "Previous reports have mentioned two isoforms of FBXO5, but the mechanisms behind their generation and their roles in different cancers remain to be explored, as does the regulatory effect of splicing factors on FBXO5." (PMID 39057099, 2024). "The present research was intended to systematically investigate the latent roles of FBXO5 in prognosis and immunological function across cancers." (PMID 35720327, 2022). "From this point of view, the correlations between the expression levels of FBXO5 and the infiltration abundance of 24 distinct immune cell subtypes were analyzed at a pan-cancer level using the ImmueCellAI database." (PMID 35720327, 2022). "Of note, elevated expression of FBXO5 was significantly related to an unfavorable prognosis in many cancer types." (PMID 35720327, 2022). "Rising FBXO5 expression was confirmed to be remarkably correlated with unfavorable clinical outcomes in a variety of cancers." (PMID 35720327, 2022). "It was revealed that immune cell infiltration degree was strongly related to FBXO5 expression in most cancers." (PMID 35720327, 2022). "In most cancers, FBXO5 expression was highly related with the levels of immune checkpoint gene expression." (PMID 35720327, 2022). "In consequence, it is urgent to elucidate the significance and role of FBXO5 expression and alteration across different cancers." (PMID 35720327, 2022). "Apart from those tumors with no available normal tissue data including MESO and UVM, statistical significance of FBXO5 expression differences between normal and tumor samples was detected in 27 types of cancers." (PMID 35720327, 2022). "In brief, these results offered a theoretical basis for interpreting the oncogenic role and immunological function of FBXO5 in pan-cancer." (PMID 35720327, 2022). "Further investigation of BIRC5, H2AFZ, HIST1H2BK, KIF15, UBE2S, and FBXO5 is crucial to broaden the understanding of cancer invasion and migration, and to promote the discovery and evaluation of new therapeutic targets." (PMID 35406376, 2022). "Further demonstration revealed that abnormal FBXO5 expression in most cancers was significantly correlated with TME, immune infiltration, DNA methylation, immune checkpoints, TMB, MSI, and MMR." (PMID 35720327, 2022). "Our data first showed a significant increase of FBXO5 expression in 24 cancers, while decrease in KICH, LAML, and THCA in contrast to the corresponding normal tissues." (PMID 35720327, 2022).
cancer (continued). "These discoveries expanded the knowledge about the roles of FBXO5 in tumorigenesis and progression, proposing new insights for personalized cancer immunotherapy." (PMID 35720327, 2022). "Targeted inhibition of FBXO5 may represent a novel therapeutic strategy for treating cancer patients with FBXO5 overexpression." (PMID 40534867, 2025). "Furthermore, both chemokine and chemokine-receptor genes were strongly co-expressed with FBXO5 in pan-cancer." (PMID 35720327, 2022). "Afterwards, the correlations of expression levels between FBXO5 and immune-related genes that encode immune-activating, immunosuppressive, chemokine, chemokine-receptor proteins as well as MHC were investigated across cancers." (PMID 35720327, 2022). "Besides, FBXO5 expression levels in various tumors were assayed by the TCGA database, and the findings illustrated that from the 33 cancer tissues analyzed, FBXO5 was expressed with the lowest expression in KICH and with the greatest expression in TGCT." (PMID 35720327, 2022). "In conclusion, the present research demonstrated that FBXO5 was a potential oncogene that could serve as an independent prognostic biomarker in various cancer types." (PMID 35720327, 2022). "Regarding the top genes present in these terms, we found genes involved in carcinogenesis with potential prognostic and therapeutic roles in cancer (FBXO5 and SMC4) and also PRC1, whose deregulation is related to chromosomal instability and tumor heterogeneity." (PMID 35954157, 2022). "Moreover, the comparison of FBXO5 expression across different pathological stages of each cancer type was assessed, which indicated that FBXO5 expression was higher in more advanced stages of the four malignancies, namely ACC, KICH, LIHC, and UCEC." (PMID 35720327, 2022). "Because of its crucial roles in cancer immunity and tumorigenesis, FBXO5 may serve as a novel prognostic indicator and immunotherapeutic target for various malignancies." (PMID 35720327, 2022). "Therefore, increased expression of FBXO5 can make tumor cells more sensitive to most kinds of compounds, which implies that the therapies of most compounds become effective in cancer patients with high FBXO5 expression." (PMID 35720327, 2022). "Additionally, considering the essential roles of TMB and MSI in the prediction of the response to immune therapy across cancers, the link between FBXO5 expression and the values of TMB or MSI was also explored." (PMID 35720327, 2022). "FBXO5 is also suggested to play an emerging oncogenic role in human cancers." (PMID 30341246, 2019). "Additionally, cluster statistical analysis revealed that FBXO5 expression is more pronounced in malignant tumors compared to benign tumors, indicating that there is a significant dysregulation of mitotic APC/C substrates in malignancies, which is absent in benign growths." (PMID 39057099, 2024). "In summary, our findings proposed a comprehensive view of the oncogenic role of FBXO5 in multiple kinds of cancers and suggested that FBXO5 might function as a viable indicator for predicting clinical prognosis and immune therapy response in cancer patients." (PMID 35720327, 2022). "On the other hand, for the aim of exploring the correlation between FBXO5 promoter methylation and survival prognosis (OS, DSS, DFI, and PFI), Kaplan-Meier analyses were performed for the 33 forms of cancers studied." (PMID 35720327, 2022). "For the purpose of clarifying the correlation between FBXO5 expression and tumor prognosis, hazard ratio statistics for OS, DSS, DFI, and PFI were processed via forest plots for each cancer included in this study." (PMID 35720327, 2022). "The present data uncovered that FBXO5 expression had a general relationship with multiple immune checkpoint genes and MMR genes in most cancers." (PMID 35720327, 2022).
cancer (continued). "Next, CNA analyses revealed that each gene is frequently altered in 10 common cancer types, and that SKP1, RBX1, FBXW7 and FBXO5 tend to exhibit more losses, while CUL1 and SKP2 exhibit more gains." (PMID 35008511, 2021). "FBXO5, which is also known as EMI1 and FBX5, has been identified as an endogenous inhibitor of the anaphase-promoting complex or cyclosome (APC/C) that plays an oncogenic role in human cancers." (PMID 30999935, 2019). "F-Box Protein 5 (FBXO5, also named Emi1) is a regulator of anaphase promoting complex/cyclosome (APC/C) activity in mitotic and meiotic cell cycle regulation and was reported to be overexpressed in a variety of cancer cells and enhance cancer progress." (PMID 39061113, 2024). "Furthermore, deficient mismatch repair (dMMR) is an unneglected mechanism of tumorigenesis and development, which suggests that the potential relationship between FBXO5 and MMR needs to be studied in pan-cancer." (PMID 35720327, 2022). "The results suggested that FBXO5 was expressed at a high level in numerous tumor cell lines with significant upregulation in most cancers as opposed to normal tissues." (PMID 35720327, 2022). "At present, specific studies on FBXO5 in tumors appear to be restricted to certain human cancers, but lack of systematic pan-cancer investigation." (PMID 35720327, 2022). "On the contrary, a negative relationship with FBXO5 expression existed in diverse cancers." (PMID 35720327, 2022). "Besides, a close positive correlation between FBXO5 expression and infiltrating macrophages was observed in PRAD (p-value < 0.0001), whereas a notable negative correlation was identified in GBM, THCA, and THYM (p-value < 0.0001 for the three cancers)." (PMID 35720327, 2022). "To gain novel insight into cancer pathogenesis, we determined the prevalence of genetic and epigenetic alterations in six prototypic SCF complex member genes (SKP1, CUL1, RBX1, SKP2, FBXW7 and FBXO5) from patient datasets extracted from The Cancer Genome Atlas (TCGA)." (PMID 35008511, 2021).
tumor (23 papers, 2016 to 2025). "Further, GSEA and GSVA were carried out to explore the underlying biological relevance of FBXO5 in tumor tissues." (PMID 35720327, 2022). "Through real-time PCR and IHC analysis, we found that FBXO5 knockdown tumor tissues showed increased CHOP expression." (PMID 38212299, 2024). "By mediating ubiquitination-mediated degradation of RNF183, FBXO5 prevents ER stress-induced apoptosis and facilitates tumor growth." (PMID 38212299, 2024). "Compared with the control knockdown group, the FBXO5 knockdown group displayed significantly smaller tumor volume and lighter tumor weight in nude mice." (PMID 38212299, 2024). "F-box protein 5 (FBXO5), an essential subunit of the ubiquitin protein ligase complex, is increasingly recognized to exhibit important biological effects in regulating tumor occurrence and progression." (PMID 35720327, 2022). "Taken together, these results implied that high FBXO5 expression generally contributed to unfavorable patient prognosis and survival in a variety of tumor types." (PMID 35720327, 2022). "ROC curve indicated that CCNB2, FBXO5, KIF4A, MCM10, and TPX2 exhibited excellent diagnostic efficiency for normal and tumor tissues." (PMID 30254986, 2018). "Given the known role of FBXL2 as a tumor suppressor gene in various tumors, we focused on FBXO5." (PMID 38212299, 2024). "Furthermore, when RNF183 was silenced in conjunction with FBXO5, tumor growth was restored, as evidenced by consistent conclusions drawn from statistical analyses of tumor volume and weight." (PMID 38212299, 2024). "Furthermore, silencing RNF183 enhanced the proliferative capacity of tumor cells and restored the proliferation ability of cells following FBXO5 silencing." (PMID 38212299, 2024). "FBXO5, a protein-coding gene, is highly expressed in a variety of primary tumors and promotes tumor progression, however, its role and prognostic value in CC remain largely unknown." (PMID 37457292, 2023). "Based upon these findings, FBXO5 may perform an integral function in cell cycle abnormalities and the disruption of genomic stability, both of which can enhance tumor growth." (PMID 35720327, 2022). "Moreover, differential expression levels of FBXO5 across tumor and normal samples were computed with the aid of the TCGA database." (PMID 35720327, 2022). "Hence, for evaluating the potential of FBXO5 in guiding clinical treatment, the correlation between FBXO5 and drug resistance of tumor cells was computed based upon IC50 values of drugs along with FBXO5 expression levels." (PMID 35720327, 2022). "Notably, the fold change of upregulation of FBXO5 expression levels among tumor tissues was the highest in GBM compared with the corresponding normal tissues." (PMID 35720327, 2022). "Meanwhile, FBXO5 expression was analyzed to be correlated with the tumor stage." (PMID 35720327, 2022). "To conclude, these data inferred that FBXO5 might contribute to regulating immune cell infiltration and the biological functions of various immune-related genes in the tumor immune microenvironment of most tumor types." (PMID 35720327, 2022). "Additionally, the paired differential expression analysis of FBXO5 among tumor and normal tissues was performed followed by a paired Student’s t-test." (PMID 35720327, 2022). "Prospective studies focusing on tumor immunity and FBXO5 expression may be beneficial in providing a definite answer, thereby facilitating the development of an immunotherapy approach targeting FBXO5 for tumor in the future." (PMID 35720327, 2022). "Existing evidence has suggested that FBXO5 affects tumor prognosis and clinical phenotypes." (PMID 35720327, 2022). "While the majority of genes we tested did not affect tumor growth or latency, overexpression of Fbxo5 caused a significant delay in tumor formation." (PMID 30659187, 2019).
tumor (continued). "Moreover, FBXO5 expression was remarkably positively correlated with the levels of infiltrating Treg cells and Tcm cells in most tumors, but negatively correlated with tumor-infiltrating CD8+ T cells, NK/NKT cells, and Th2 cells." (PMID 35720327, 2022). "Thus, FBXO5 might be taken as a viable biomarker for indicating the immunotherapy response in these tumor types." (PMID 35720327, 2022). "Subsequently, we monitored apoptotic markers and found that with FBXO5 silencing, increased expression of RNF183 led to augmented Caspase3/7 activity, leading tumor cells towards apoptosis." (PMID 38212299, 2024). "Several F‐box containing proteins have been characterized either as tumor suppressors (FBXW8, FBXL3, FBXW8, FBXL3, FBXO1, FBXO4, and FBXO18) or as oncogenes (FBXO5, FBXO9, and SKP2)." (PMID 33822486, 2021). "β-TRCP has previously been shown to function as a tumor suppressor by targeting various oncoproteins such as β-catenin, CDC25A, FBXO5, IκB and DEP domain-containing mTOR-interacting protein (DEPTOR)." (PMID 29497989, 2018). "As for FBXO5, FBXO22, FBXO28, FBXO31 and FBXO45, they may be the independent poor prognostic factors of BC and the expression levels of which were closely related to different tumor stages." (PMID 33622332, 2021).
infection (3 papers, 2014 to 2020). The state of being infected such as from the introduction of a foreign agent such as serum, vaccine, antigenic substance or organism. "An shRNA targeting FBXO5 was designed and introduced into hPDLSCs via lentiviral infection." (PMID 29850565, 2018). "Infection of shRNAs against eight F-box proteins (FBXL5, FBXW5, FBXO3, FBXO4, FBXO5, FBXO24, FBXO25 and FBXO27) upregulated Snail1 protein levels (at least by 2-fold) compared with parental cells or cells infected with a control shRNA." (PMID 24157836, 2014).
FBXO5 also shares sentences with these, for which no sentence is quoted: ovarian carcinoma (3 papers); squamous cell lung carcinoma (3); benign tumors (2); esophageal squamous cell carcinoma (2); prostate carcinoma (2); adenocarcinoma of the colon (1); chronic myeloid leukaemia (1); clear cell carcinoma (1); embryonal carcinoma (1); Fanconi's anaemia (1); Hepatitis (1); hepatitis C (1); infectious disease (1); lung adenocarcinoma (1); lymph node metastasis (1); mantle cell lymphoma (1); ovarian tumors (1); Renal Cell Cancer (1); retinoblastoma (1); serous ovarian carcinomas (1).